IL17A (interleukin 17A)
Diseases named in the same sentence as IL17A in open-access papers (continued):
Sharing a sentence is not in itself a finding about the gene and the disease.
infection (continued). "IL-17A production in P. aeruginosa-specific immune responses following infection." (PMID 27698020, 2016). "We used anti-IL-17A or IL-17F antibody (500 μg/mouse, 20 mg/kg) or anti-TNFα antibody (250 μg/mouse, 10 mg/kg) or the respective isotype control IgG antibodies, administered weekly, starting 1 day before infection." (PMID 27853279, 2016). "However, all patients had significantly lower serum IL-17A values compared to candidemic patients suggesting Candida colonization in contrast to infection." (PMID 27206014, 2016). "IL-17A plays a critically important role in mucosal surface resistance to infection by both extracellular and intracellular bacterial pathogens, as animals deficient in either IL-17A or its receptor, IL-17RA, demonstrate increased susceptibility to bacterial infection." (PMID 27723765, 2016). "Both IFN-γ and IL-17A was significantly increased in RRV group at day 7 after RRV infection." (PMID 26325187, 2015). "In addition, both IFN-γ and IL-17A levels were negatively correlated with the CSF baseline CFU count remarking their relevance to the infection control." (PMID 25799044, 2015). "Similar with the supplement of leucine, Ad-S6K1 infection could titer-dependently reverse the down-regulated mRNA expression of RORγt and IL-17A by ghrelin, and increased the secretion of IL-17A in supernatant." (PMID 25658305, 2015). "At a time-point of infection in which T. borreli induced higher levels of IFNγ expression than induced by T. carassii, only T. carassii induced enhanced IL-17A/F expression, which was accompanied by a marked neutrophil infiltration into the spleen of only T. carassii-infected fish." (PMID 26593954, 2015). "In a later study, it has been shown that pro-inflammatory T-cell response consisting of IL-17A and IFN-γ producing TH17 cells caused EAE in germ-free mice upon infection from Segmented Filamentous Bactria (SFB), further linking gut dysbiosis and neuronal autoimmunity." (PMID 26779152, 2015). "In malarial infection, MyD88 deficiency results in severe impairment of IL17A producing γδT cells levels, but not IFNγ producing γδT cells highlighting differential control by innate signaling through TLRs in infections." (PMID 25699053, 2015). "By contrast, cytokines involved in Th17 signal transduction, such as IL-17A, IL-17F or IL-21, were highly up-regulated after infection, and the Th17 pathway is known to contribute to inflammation and influx of neutrophils to the site of infection." (PMID 25719526, 2015). "However, il-17a gene expression was reduced in the lungs of both wild-type and IL-13tg mice early after infection, but comparable thereafter." (PMID 24979482, 2014). "IL-17A is thought to be an essential cytokine that regulates pathogenesis in multiple infections." (PMID 24392094, 2014). "Neutrophil recruitment was mediated by IL-17A in the first 24 h following viral challenge and could efficiently be blocked in the early phase of infection by antibodies neutralizing IL-17A." (PMID 24918427, 2014). "Finally, we found elevated IL-23 and IL-17A levels in the serum of patient 1, in the first days following the infection by MERS-CoV." (PMID 24551142, 2014). "This might be due to an induction of cytokines during the progression of the infection, which could overcome the effect of IL-17A." (PMID 24918427, 2014). "For instance, IL-17A directly activates macrophages and dendritic cells to produce various cytokines including IL-12, which enhances Th1 immunity and host defense against infection by the intracellular bacteria, Francisella tularensis." (PMID 23383714, 2013). "However, at day 254 of infection, Mtb-specific IL-17A-producing CD4+ T cells were significantly enhanced in IL-22−/− mice." (PMID 23460846, 2013).
infection (continued). "With respect to immunity to infection, we have previously reported that increased resistance to the helminth parasite Schistosoma mansoni following drug treatment and IL-10R blockade led to elevated antigen-specific IFNγ, IL-5 and IL-17A production." (PMID 23345540, 2013). "Like IL-17A, IL-22 is expressed early after infection with Mtb in an IL-23-dependent manner." (PMID 23460846, 2013). "Therefore, the results confirm that the delivery of Ad-IL-17AR:Fc reduces the expression of IL-17A on day 90 post-infection in chronic CVB3 myocarditis." (PMID 23977238, 2013). "Importantly, the production of IFN-γ and IL-17A by CD4+ T cells isolated from mice during the primary infection (3 dpi) was significantly lower than that observed upon re-challenge." (PMID 23853597, 2013). "IL-17A-producing iNKT cells comprise up to 40% of pulmonary iNKT cells and may also be responsible for the infection with Streptococcus pneumonia." (PMID 23956759, 2013). "The induction of IL-17A, which was secreted from T-helper 17 (Th17) cells, may be an infection defense reaction to the pathogens such as fungi that adhere to ASD." (PMID 23731974, 2013). "This more sensitive method of detecting IL-17A may reveal a similar, small role and function for γδTCR+ cells during infection with virulent F. tularensis as that observed with attenuated bacteria." (PMID 22428026, 2012). "However, significantly increased IL-17A+/CD3+ and IL-17A+/γδ+ T cell populations were also observed in the lungs of IL-17RA−/− mice compared to wild-type mice on day 7 post-infection." (PMID 23216912, 2012). "Therefore, we sought to determine the effect of neutrophil depletion on IL-17A production in the lungs of mice during infection with C. neoformans strain H99γ." (PMID 23216912, 2012). "Consistently, a significant reduction of iNOS expression in the IL-17A-neutralized mice was observed in comparison with IgG2a-treated mice at day 7 after infection, which further suggests that the inhibitory role of IL-17A on Cm growth involves enhancing iNOS expression." (PMID 22745717, 2012). "Additionally, protein homogenates were prepared from lung tissues on day 7 post-infection to evaluate pulmonary IL-17A cytokine production and fungal burden in neutrophil depleted mice compared to isotype control antibody treated animals." (PMID 23216912, 2012). "In contrast, the expression of other regulatory cytokines such as IL2, IL6 and IL17a (not shown) were not significantly different in resistant and susceptible contexts, nor affected by infection." (PMID 22720048, 2012). "We analyzed levels of pro-inflammatory IL-17 members (IL-17A, IL-17B and IL-17F) as well as their soluble common receptors (IL-17RA and IL-17RB) in clinically staged AE patients, that is, cured, stable, and progressive AE, and in infection-free controls." (PMID 22969818, 2012). "Consequently, we evaluated IL-17A production in IL-17RA−/− mice compared to wild-type mice on day 7 following infection with C. neoformans strain H99γ." (PMID 23216912, 2012). "Indeed, we determined that during T. cruzi infection not only IL-17A but also IL-17E and IL-17F are produced during the peak of the infection." (PMID 22577359, 2012). "In contrast, we did not observe any change in neutrophil recruitment in mice treated with anti-IL-17A antibodies, further suggesting that IL-17A alone was not required to induce neutrophil recruitment to the lungs in response to C. neoformans H99γ infection." (PMID 21359196, 2011). "Interestingly, CTC administration only decreased expression of IL-17A mRNA at the late stage of infection in the current study, perhaps due to the concomitant down-regulation of TNF-α and IL-1β mRNA expression." (PMID 21943280, 2011). "After a single infection 20-39% of the 2W-specific T cells produced IL-17A." (PMID 21966268, 2011). "The elevated IL-17A serum level also indicates a long period of infection in the patients observed." (PMID 22308123, 2010).
infection (continued). "Moreover, when enough time was allowed (day 4 of infection) the amounts of IL-17A in BALFs of mice infected with 100 CFU was found to be equivalent to that induced by infection with 105 CFU." (PMID 20585449, 2010). "In another very recently published report, the protective role of IL-17A against intradermal LVS infection was demonstrated with IL-17A knockout mice, while effects of exogenous cytokines promoting the IL-23/IL-17A axis were demonstrated in vitro in an intracellular LVS growth system." (PMID 20585449, 2010). "We therefore hypothesized that IL-17A should be administered directly to the target organ of infection, the respiratory tract." (PMID 20585449, 2010). "Among CD4+ T cells, IL-17A-producing cells reached the peak on day 6 post-infection (A2)." (PMID 20585449, 2010). "This profile could thus suggest that IL-17A is involved in restraining the infection and preventing it from becoming fulminant." (PMID 20585449, 2010). "Here we show that IL-17A is produced in the lungs in response to airway LVS infection." (PMID 20585449, 2010). "In unvaccinated animals, deficiency in IFN-γ but not IL-17A exacerbated the severity of iv infection caused by both S. aureus and C. albicans." (PMID 20041174, 2009). "Of note, in contrast to IFN-γ deficiency, IL-17A deficiency did not exacerbate the severity of infection in unvaccinated mice (comparing survival of unvaccinated, deficient vs. wild type mice)." (PMID 20041174, 2009). "Therefore, clarifying whether Th17 cells/IL-17A exert protective or detrimental effects during infections is essential for effectively controlling disease progression." (PMID 41402924, 2025). "Furthermore, genes involved in Th17 cell/IL-17A maturation were significantly upregulated during PmCQ2 infection, suggesting that Th17 cells/IL-17A may play a key role in PmA infection." (PMID 41402924, 2025). "However, at early time points after infection, dermal γδ T cells may moderate wound healing, at least partially, via production of IL-17A in response to cutaneous VACV infection." (PMID 38543790, 2024). "Furthermore, vaccinated mice deficient in IL-17A were not protected following S. pyogenes URT infection, demonstrating a role of IL-17A which in turn is ‘regulated’ by macrophages and neutrophils." (PMID 37749129, 2023). "Furthermore, we identified that Vγ6+ cells also upregulated Il17a during infection." (PMID 37923768, 2023). "Moreover, IL-17A is expressed stably throughout the murine infection period, suggesting that gonococci may maintain this polarization throughout infection." (PMID 36819065, 2023). "In the current study, IL-17A responses induced by a C18Brar formulated vaccine against M. haemolytica and M. ovipneumoniae could potentially enhance protective immunity against natural infection in sheep." (PMID 36656850, 2023). "However, intestinal IL-17A expression was comparable between WT and muMT mice during infection." (PMID 38203534, 2023). "Thus, we believe that in the initial phase of infection by T. canis, the cytokines IL-17A and IL-4 are the main active components, however, a synergistic action with other components of the immune system is necessary for a more effective and controlled response." (PMID 35844540, 2022). "Our result that after infection with an elevated dose of Mtb, IL-17A−/− mice partially exhibit enhanced recruitment of neutrophils in the lung is in stark contrast to the finding that IL-17A appears to be closely involved in the induction of neutrophils in response to infection with Mtb." (PMID 36139450, 2022). "Furthermore, the Th17 cell amount in IFN-γ-deficient mice is elevated in contrast to WT mice and might be upregulated to combat infection via IL-17A because IFN-γ is missing." (PMID 35446923, 2022). "Consequently, the strong accumulation of Mtb-containing neutrophils in the absence of IL-17A indeed partially accounts for the increased susceptibility to infection with high doses of Mtb H37rv." (PMID 36139450, 2022).
infection (continued). "Since it has been demonstrated that the requirement of IL-17A for protective immune responses to Mtb depends on the virulence of the Mtb strain used for infection, we speculated that IL-17A may similarly mediate protection after infection of the experimental mice with an elevated dose of Mtb H37rv." (PMID 36139450, 2022). "Orally available IL17A small molecule antagonists could extend these benefits to a larger number of patients who dislike the needle-based injections needed to administer such anti-IL17 antibodies or need to more quickly wash out IL17 antagonism in the event of fungal or other infections." (PMID 36028520, 2022). "For example, IL-17A production increases in Mtb infected neutrophils and autocrine IL-17A-production by neutrophils was vital for inhibiting Mtb growth by neutrophils through increased reactive oxygen species production and their migration to the site of infection." (PMID 35976976, 2022). "Intramammary infusion of IL-17A in the mammary gland of mice infected with E. coli has helped to control the infection, suggesting that increasing the local production of this cytokine early in the course of infection could be beneficial." (PMID 35214754, 2022). "Taken together with the data from the Il17A−/− mice, our findings suggest IL-17 plays an essential role in natural immunity induced by the previous infection in the nasal mucosae, and that this may be mediated by recruitment of neutrophils, especially Siglec-F+ neutrophils." (PMID 33976385, 2021). "IL-4 receptor blockade is shown to promote Il17a expression and enhance bacterial clearance in tape-stripped mouse skin exposed to S. aureus, suggesting that it could serve as a therapeutic approach to prevent skin and soft tissue infection." (PMID 34747366, 2021). "IL-1 and IL-23, which may be derived in part from keratinocytes, were required for the induction of IL-17A following S. aureus infection of mechanically injured skin, consistent with the important role of these 2 cytokines in the induction of IL-17A in inflammation, infections, and wound healing." (PMID 34747366, 2021). "Finally, we examined neutrophil recruitment to the site of infection in Il17A−/− and WT mice." (PMID 33976385, 2021). "On the other hand, local levels of IL-17A in culture negative mice were lower than the average, which could be linked to the resolution of the infection or could indicate a role in active infection." (PMID 34240122, 2021). "Interestingly, IL17A was induced sharply by GS2018 infection in this study." (PMID 34872498, 2021). "Mice lacking IL-17A and/or IL-17A receptors are highly susceptible to various pathogens, such as Staphylococcus aureus, Candida albicans and Klebsiella pneumoniae, which have increased colonization rates, leading to higher host mortality rates after infection." (PMID 33879639, 2021). "In addition, in vivo studies have revealed that IL-17A exacerbates the severity of lung infection as evidenced by the increase in serum IL-17A levels upon infection with Mycobacterium pulmonis and reduction in disease severity by neutralization of IL-17A in Balb/c mice." (PMID 33419073, 2021). "Thus, it would be interesting to know what cells might be involved in the production of IL-22 during the infection, and more so if IL-22 is somewhat produced in the same manner or maybe regulated differently with IL-17A during R. anatipestifer infection." (PMID 34805416, 2021). "Similarly, high levels of IL‐17A, IL‐10 and sE‐selectin were measured in patients with all endovascular infections (IE + non‐IE) vs. extravascular foci, as well as non‐IE endovascular infections vs. extravascular foci." (PMID 32082571, 2020). "Therefore, we sought to determine IL-17A expression during HN878 infection." (PMID 32198367, 2020).
infection (continued). "Overall, our data demonstrated that IL-17A-deficiency enhanced IFNγ production during infection, supporting the hypothesis that IL-17A plays an important role in downregulating IFNγ at the site of infection during the lung migratory phase of N. brasiliensis infection." (PMID 32636457, 2020). "However, the continued or robust expression of Th17 cytokines IL-17A and IL-22 during early infection is reliant on the presence of IL-23, which could be supplied by MAP-infected macrophages." (PMID 32258066, 2020). "However, IL-17A may play more of a protective role as it seems to be upregulated in early infection but is downregulated in late clinical disease, similar to what is observed with IFNγ." (PMID 32258066, 2020). "In resistant hosts, IL-17A contributes to the formation of a mature granuloma which constrains the multiplication of Mycobacterium tuberculosis (M.tb) clinical isolates and plays a protective role.This is particularly observed during infection with hypervirulent M.tb strains." (PMID 31736982, 2019). "Moreover, pathways such as “IL-10 signaling,” “IL-6 signaling,” “NF-kB signaling,” “Acute phase response signaling,” and “Differential regulation of cytokine production in macrophages and T helper cells by IL-17A and IL-17F” showed strong regulation of immunity-related genes during early infection." (PMID 31969876, 2019). "In hosts which are susceptible to progress toward active disease, PI3Kγ may be downregulated from the initial point of infection throughout the progression and establishment of disease resulting in the over secretion and therefore pathological potential of IL-17A." (PMID 31736982, 2019). "IL-17A is known as an inflammatory cytokine whose main function is exerted on myeloid and mesenchymal cells by inducing the expression of granulocyte colony-stimulating factor (G-CSF), IL-6, and other chemokines, which increase granulopoiesis and recruit neutrophils into the site of infection." (PMID 29805810, 2018). "SFB in Tac B6 mice of our study persistently and predominantly colonized the ileum irrespective of infection status, which was associated with over 100-fold increase of ileal Il-17A mRNA, but not Tnfα and Il-1β mRNA when compared to both H. pylori infected and control Jax mice." (PMID 29789574, 2018). "Overall, these findings show that Th17 signalling, especially IL-17A secretion, is an important player within the complex defence mechanisms of the host but might also be beneficial for the survival of the helminth in the early phases of infection." (PMID 29931394, 2018). "Interestingly, there was an early increase in IL-17A concentration at 18 hpi in the milk of almost all goats, suggesting that IL-17A induction is a component of the immune response of the goat mammary gland to infection by S. aureus." (PMID 30045763, 2018). "Moreover, subcutaneous L. sigmodontis infection with a defined number of infective larvae and analysis of earlier infection time points between days 0–9 p.i. might decipher the role of IL-17A for parasite clearance during L3 migration into the TC." (PMID 29931394, 2018). "Also, absence of Casz1 caused a significant diminution in IFN-γ+IL-17A+ iTh17 cells (Th1*) in draining LN and tongue during secondary infection." (PMID 29467767, 2018). "Besides, the IL-17A-producing γδ T cells which are activated rapidly following L. monocytogenes infection mediate its antibacterial immune response via IL-23 production by pathogen-activated macrophages/DCs during the early phase of infection." (PMID 30116753, 2018). "However, there is controversy over whether IL-17A is involved in resisting S. pneumoniae lethal infections." (PMID 28659923, 2017). "Furthermore, there is evidence from experimental VL that the impact of IL-17A may depend of the stage of infection, whereby this cytokine impedes antiparasitic immunity early, but is protective following establishment of infection." (PMID 29167671, 2017).